INS (insulin)
Diseases named in the same sentence as INS in open-access papers (continued):
Sharing a sentence is not in itself a finding about the gene and the disease.
diabetes (continued). "Given that cardiovascular diseases are also associated with insulin resistance, and insulin is known to induce vasodilation via a NO-dependent pathway, we hypothesised that abnormal insulin modulation of L-arginine transport may contribute to vascular dysfunction in diabetes." (PMID 23658699, 2013). "As expected, CSII initiation resulted in fewer non-insulin diabetes medications prescribed in type 2 patients, which highlights the effectiveness of this insulin intensification approach." (PMID 27536441, 2013). "A 70-year-old Chinese woman with a history of diabetes mellitus and insulin therapy had severe hyponatremia and gastrointestinal symptoms." (PMID 23734852, 2013). "Insulin resistance as measured by fasting insulin, fasting glucose, diagnosis of diabetes mellitus and HOMA-IR were also predictive of normal histology." (PMID 23658732, 2013). "Compared to the non-diabetes, the plasma insulin level was relatively lower in the diabetic monkeys (11.2 ± 4.8 μIU/ml, n = 5) and remained unchanged during 90-min observation after xylazine administration (solid cycle)." (PMID 24138083, 2013). "It is a brain specific form of diabetes characterized by impaired insulin actions and neuronal insulin resistance that leads to excessive generation and accumulation of amyloid oligomers, a key factor in the development of AD." (PMID 23415113, 2013). "We also found a higher prevalence and longer duration of the insulin-treated diabetes and active smokers among the SVGD (+) patients." (PMID 24151618, 2013). "There was not significant difference in ratio of male/female patients, age, diabetes duration, insulin therapy, weight, BMI, waist circumference or systolic or diastolic blood pressure between the groups." (PMID 23410093, 2013). "When advised to start insulin, some patients felt that their diabetes was worsening while others denied the need for insulin." (PMID 24282518, 2013). "Over the past 30 years, the introduction of multiple insulin formulations, each of which has a different duration of action, has enriched the therapeutic armamentarium for the management of diabetes." (PMID 24124913, 2013). "In South Africa, in 1982–2002, Gill and co-workers identified a cohort of patients with diabetes requiring insulin therapy diagnosed before age 30 years." (PMID 22817387, 2013). "The results of the present study clearly demonstrated that the plasma levels of (10- and 12-(Z,E)-HODE)/LA correlated significantly with several important clinical values for the diagnosis of diabetes, such as HbA1c, glucose, and insulin-related indices." (PMID 23691063, 2013). "Emerging evidence has demonstrated that BBR has multiple beneficial effects, such as lipid-lowering, hypoglycemic, insulin-sensitizing, and weight-lowering properties in diabetes and cardiovascular diseases." (PMID 23555784, 2013). "In this way, tissue targeted deletion of PTEN leads to improved insulin sensitivity in the insulin-responsive tissues and protects from diabetes." (PMID 23431468, 2013). "Plus, while the majority of type 2 patients stopped all non-insulin diabetes medications with the lone exception of metformin, one patient began a GLP-1 agonist, albeit only for a short period of time." (PMID 27536441, 2013). "It was known that insulin-resistant patients, such as those affected by obese T2D at the beginning of diabetes natural history, showed increased levels of circulating insulin." (PMID 23750710, 2013). "These diabetic mice exhibited the classical features of STZ-induced diabetes: i.e.; severe hyperglycemia, hyperphagia, low body weight gain, and low insulin concentration." (PMID 23967137, 2013). "Using the Glucose Buddy application, patients logged 24,720 diabetes parameters in total: 54.00% (13,349/24,720) of the logs related to blood glucose levels, 33.00% (8158/24,720) to insulin, 12.00% (2966/24,720) to diet, and 1.00% (247/24,720) to exercise." (PMID 24225149, 2013).
diabetes (continued). "Metformin, an insulin sensitizer, is a first line and most commonly used drug in management of diabetes, either as initial or combination therapy." (PMID 23476808, 2013). "The Brazilian government aids patients with diabetes by providing the equipment and supplies (glucometer and glucose test strips) needed for BG self-monitoring for patients who are using insulin." (PMID 24011173, 2013). "The majority of patients were on diabetes medications (81.7%) and 33% of the patients were on insulin treatment." (PMID 24260240, 2013). "Many oral antihyperglycemic agents, such as sulfonylurea and biguanides, are available along with insulin for the treatment of diabetes, but these agents have significant side effects, and some are ineffective in chronic diabetes patients." (PMID 23509685, 2013). "STZ-NIC-mediated diabetes induction in rats increases HbA1c levels and reduces serum insulin, Hb, and TP significantly (P < 0.001) when compared to normal control rats." (PMID 23936668, 2013). "Weight loss decreases the amount of adipose tissue in thigh muscle and improves insulin sensitivity in people with obesity or type 2 diabetes mellitus." (PMID 23892710, 2013). "Wolfram Syndrome patients present with diabetes mellitus and diabetes insipidus, which result from compromised production of insulin by the pancreas and of vasopressin by the pituitary, respectively." (PMID 23703906, 2013). "Increasing evidence indicates that type 2 diabetes mellitus resulting from insulin insensitivity can give rise to a wide range of complications in the central nervous system (CNS), including cognitive decline and development of dementia." (PMID 23593231, 2013). "Insulin therapy is still the gold standard in the treatment of diabetes in pregnancy when medical nutrition therapy (MNT) and lifestyle cannot reach and maintain the metabolic targets." (PMID 23840206, 2013). "Bivariate analysis showed (marginally) significant associations between the practice score and level of education, marital status, mode of diagnosis, duration of disease, insulin use and frequency of seeing diabetes educator." (PMID 23341913, 2013). "The Scottish Care Information-Diabetes Collaboration database registry (N = 36,254) showed that mean HbA1c levels were 8.6–9.4% in type 1 or 2 diabetes patients treated with insulin." (PMID 24011395, 2013). "To this aim, we retrospectively evaluated pregnancy outcome in women with GDM or type 2 diabetes mellitus treated with ILPS or NPH insulin." (PMID 23840206, 2013). "Taken together, evidence from a plethora of studies indicates that ceramide plays a significant role in diabetes by at least three different mechanisms: inducing pancreatic β-cell apoptosis, increasing insulin resistance, and reducing insulin gene expression." (PMID 23835113, 2013). "Type-1 diabetes (T1D) is an insulin-dependent form of diabetes with high mortality and morbidity rates, which usually begins in childhood and adolescence." (PMID 23367498, 2013). "The complex (IGF-I/IGFBP-3) formed can be used to treat growth hormone insensitivity syndrome (GHIS) and reduce insulin requirement in patients with diabetes." (PMID 24143239, 2013). "Type 1 diabetes, which accounts for 5%–10% of all diabetes cases, generally results from autoimmune destruction of insulin-secreting pancreatic islet cells." (PMID 23841102, 2013). "Univariate and multiple logistic regression analyses showed that diabetes duration, insulin therapy, and prolonged poor glycemic control (HbA1cmedian) were the main predictors of retinopathy in patients with type 2 diabetes." (PMID 24363502, 2013). "Though insulin sensitizers (i.e., biguanides and thiazolidinediones) have been shown to slow the progression of pre-diabetes to some extent, these agents have an upper dosage limitation and thus cannot be up titrated when its biological effect weakens." (PMID 23408938, 2013).
diabetes (continued). "Pancreas weight and pancreatic insulin content were measured at the end of the experiment in order to investigate the severity of diabetes mellitus in ZDF rats." (PMID 23320804, 2013). "Some 30 years ago in the USA only insulin was available for treatment of diabetes for those unresponsive to diet and exercise alone." (PMID 23841986, 2013). "There is increasing evidence linking insulin resistance to cognitive decline and dementia in diabetes." (PMID 24386004, 2013). "Activation of these pathways is linked not only to the development of the late complications of diabetes, but also to insulin resistance and β-cell dysfunction." (PMID 24324490, 2013). "In another study, it was shown that oral administration of curcumin at high dose (3% in the diet) ameliorated HF-induced diabetes as determined by glucose and insulin tolerance testing." (PMID 24260564, 2013). "IDE plays a key role in the degradation of insulin and Aβ, classic hallmarks of diabetes mellitus and AD, respectively." (PMID 23915208, 2013). "In the case of pre-diabetes, increases in blood glucose stimulate the secretion of insulin and subsequently induce hyperinsulinemia with a normal blood glucose range." (PMID 23382926, 2013). "Regarding IR remission, many studies have suggested that weight reduction improves insulin sensitivity and/or diabetes status in selected populations such as those with obesity and/or diabetes." (PMID 23717466, 2013). "The annual average insulin costs according to diabetes type in Saudi Riyals (SR) are 1155 SR (US $308), 1406 SR (US $375), and 1002 SR (US $267) for type 1, type 2, and GDM, respectively." (PMID 24025198, 2013). "Glibenclamide stimulates the insulin secretion from the β-cells of the pancreas and is extensively used to treat diabetes mellitus." (PMID 24204387, 2013). "Thiazolidinediones (TZDs) are potent PPARγ ligand and used as insulin sensitizers in the treatment of type 2 diabetes mellitus." (PMID 25374688, 2013). "Other factors affecting diabetes knowledge were sex, age, level of education, marital status, profession, income, insulin treatment, mode of diagnosis and duration of diabetes." (PMID 23341913, 2013). "The most commonly mentioned advantage was that insulin would help control diabetes and thus prevent diabetes complications." (PMID 24282518, 2013). "For example, management of diabetes often requires insulin titration based on a patient’s blood glucose readings." (PMID 23557596, 2013). "Type 2 diabetes mellitus is a heterogeneous disease characterized by insulin resistance and defective insulin secretion." (PMID 23339473, 2013). "C-peptide is produced in equal amounts to insulin and is the best measure of endogenous insulin secretion in patients with diabetes." (PMID 23413806, 2013). "Men often remain undiagnosed even after the development of diabetes requiring high doses of insulin." (PMID 23766565, 2013). "Oral administration of 1,000 mg/kg body weight per day of S. crispa for 4 weeks was shown to significantly accelerate wound healing in rats with streptozotocin- (STZ-) induced diabetes, which is an insulin-dependent model of diabetes mellitus (type 1)." (PMID 23586068, 2013). "The microarray data showed that allergy was associated with a reduction in IDE, which mediates cleavage of insulin and amyloid-β (Aβ), important proteins in diabetes mellitus and AD, respectively." (PMID 23915208, 2013). "Diabetes generally develops as pancreatic β-cells are unable to respond adequately to increased insulin required to maintain normoglycaemia." (PMID 23573093, 2013). "In these rats receiving insulin treatment, insulin levels were significantly higher at 8 weeks of diabetes than those in the untreated diabetic rats." (PMID 23991188, 2013). "In vitro studies on breast cancer cell lines showed that the serum of patients with diabetes was a slightly stronger mitogenic when using glargine as compared to detemir or insulin with intermediate duration for action." (PMID 24131755, 2013).
diabetes (continued). "Another transgenic mouse, which features diabetes and impaired glucose-stimulated insulin secretion as a result of defective expression of hepatocyte nuclear factors, showed reduced islet expression of E-cadherin." (PMID 24278783, 2013). "In this current cohort, both recently diagnosed insulin-naïve patients and those with established diabetes (ED) who were switching basal insulin were included." (PMID 23448369, 2013). "Published guidelines for the management of adult-onset non-insulin requiring diabetes have adopted a formulaic approach to patient management that can be overseen centrally and delivered by personnel with limited training." (PMID 23841986, 2013). "Previous studies showed that impaired insulin secretion is the key in conversion from normal glucose tolerance to impaired glucose tolerance and finally diabetes." (PMID 23819960, 2013). "DR group 3 had significantly longer duration of diabetes (19.35 ± 4.60 years versus 13.22 ± 5.08 years; P < 0.001) and more often insulin than OHA therapy (87/13% versus 52/48%; P = 0.009) in comparison with DR group 1." (PMID 24363502, 2013). "Therapeutic strategies aimed at repopulating insulin-producing cells show great potential for restoring glycemia in diabetes." (PMID 23542897, 2013). "Islet transplantation, characterized as a superior alternative to the exogenous administration of insulin, is thought to potentially reverse the hyperglycemia observed in cases of diabetes." (PMID 24024182, 2013). "Significant negative predictors of diabetes remission were poor preoperative glycemic control, insulin use, and longer diabetes duration." (PMID 23840207, 2013). "The available drugs for diabetes, Insulin or Oral hypoglycemic agents have one or more side effects." (PMID 23414307, 2013). "Approximately 18% of participants (n=659) required insulin to treat their diabetes (either alone or in combination with oral medications), 61% required glucose-lowering tablets (n=2196) and 21% treated their diabetes with diet and/or exercise alone (n=753)." (PMID 24131673, 2013). "On the other hand, H2O2 was related to the development of diabetes and to the impairment of glucose-stimulated insulin secretion by pancreatic islets in female albino rats." (PMID 23483930, 2013). "All women in hypertension group were receiving methyldopa (250 mg) and in diabetes group 3 women were receiving insulin and the rest were on diabetes diet." (PMID 24134697, 2013). "In the self-reported T2DM subjects, the mean diabetes duration was 9.1 ± 6.2 years and 31 (17.4%) subjects claimed to be currently receiving insulin therapy." (PMID 24112518, 2013). "Diabetes—There is Level II evidence from two randomized controlled trials that vitamin D supplementation improves insulin sensitivity and decreases insulin resistance." (PMID 24352091, 2013). "A qualitative approach allows detailed exploration of experience, feelings, beliefs and attitude of the diabetes patients in the context of insulin acceptance." (PMID 24164794, 2013). "Patients’ experiences, thoughts and opinions about SMBG need to be accounted for and considered in order to suitably inform clinical practice and public policy in the treatment and management of patients with non-insulin treated diabetes." (PMID 24119213, 2013). "Insulin resistance and insulin secretion, the metabolic predictors of diabetes development, have been investigated in the offspring of diabetic mothers in humans and animal models." (PMID 23506302, 2013). "Diabetes can be generally divided into two types: type 1 (insulin dependent) and type 2 (insulin independent), although patients of both types will have hyperglycemia." (PMID 24286086, 2013). "A total of 834 individuals had diabetes (fasting serum glucose ≥126 mg/dl, or glycosylated hemoglobin ≥6.5%,) or were being treated with oral antidiabetic drugs or insulin)." (PMID 23637851, 2013).
diabetes (continued). "The two conditions are opposite: in diabetes “fuel” is present, i.e., glucose and what is missing is the “access key” to the cells or rather insulin; while in fasting the situation is the opposite." (PMID 24027606, 2013). "Diabetes is one of the most common endocrine disorders characterized by hyperglycemia due to defects in insulin secretion, insulin function, or both." (PMID 23497689, 2013). "Except for metformin and insulin, there is a medical necessity for formal evaluation of all other currently available diabetes medications regarding their safety and efficacy in the pediatric T2DM population." (PMID 24222881, 2013). "In spite of the fact that insulin has become one of the most important therapeutic agents known to medicine, researchers have been making efforts to find insulin substitutes from synthetic or plant sources for the treatment of diabetes." (PMID 24250639, 2013). "Similar to recent-onset diabetic NOD mice, control animals with established diabetes succumbed to disease within approximately 3 weeks of the end of insulin therapy." (PMID 24205242, 2013). "Insulin sensitivity was calculated with the equation for eGDR, and MS was defined according to International Diabetes Federation criteria.Results." (PMID 23956744, 2013). "Diabetic monkeys were given enough insulin to maintain their blood glucose levels either at ~8 mM (well-controlled diabetes) or ~15 mM (poorly controlled diabetes)." (PMID 23841102, 2013). "“You accept the insulin because the bond is there and you respect him (doctor)” (4 years of insulin use/ 8 years of having diabetes)." (PMID 24164794, 2013). "She underwent a distal pancreatectomy and splenectomy, after which she developed diabetes and was placed on an insulin pump." (PMID 26425568, 2013). "Three patients developed diabetes mellitus and required insulin (one in TOS group, two in TSP group) and received treatment." (PMID 22926695, 2013). "In the context of diabetes in general and β-cell dysfunction in particular, various conditions have been proposed to trigger damages of insulin-secreting cells." (PMID 24349266, 2013). "Diabetes is a disease manifested by hyperglycemia; patients with diabetes type I demonstrate an inability to produce insulin." (PMID 26317025, 2013). "This will attenuate hormone secretion under conditions of prolonged stimulation of β-cells potentially contributing to the release of insufficient insulin to cover the organism needs and to the development of diabetes." (PMID 23826383, 2013). "Diabetes is a group of metabolic diseases which is characterized by hyperglycemia resulting from defects in insulin secretion, insulin resistance, or both." (PMID 23755114, 2013). "Mean duration of diabetes was 7.6 ±7.5 years and 44.5% of patients were on insulin therapy prior to surgery." (PMID 23537494, 2013). "In this study, we examined the changes in gene expression required for neuronal differentiation and insulin expression in adult OB NSCs during diabetes progression." (PMID 23673084, 2013). "Complete restoration of normal insulin secretion and regeneration of beta cells have been reported in various experimental models of diabetes." (PMID 23841105, 2013). "A report from the Diabetes Mellitus Insulin-Glucose Infusion in Acute Myocardial Infarction (DIGAMI 2) trial suggested that the distributions of MBL genotypes were similar to those known in the general population." (PMID 24376633, 2013). "Islet transplantation is clinically indicated to replace the insulin producing beta cell mass in patients with type 1 diabetes mellitus and therefore represents a potential cure for the disease." (PMID 23970924, 2013). "Retained and defaulted patients had significantly longer duration of diabetes, more microvascular complications, were more likely to be on insulin and less likely to have a HbA1c < 7.0% than patients discharged from clinic." (PMID 23938105, 2013).